ITGB1 (integrin subunit beta 1)
Diseases named in the same sentence as ITGB1 in open-access papers (continued):
Sharing a sentence is not in itself a finding about the gene and the disease.
tumor (continued). "Furthermore, clinically relevant genes that are associated with tumor growth such as VIM, ITGB1, FOXQ1, FN1, MSN, CXCL and TMPRSS4 were also downregulated." (PMID 32784836, 2020). "Expression of ITGB1 was significantly upregulated in HNSCC tumor tissues (P = 0.0004)." (PMID 29423074, 2018). "Moreover, the level of ITGB1 expression was also higher in all NSCLC tumor biopsies (9.43 ± 0.87) than those in normal lung tissues (3.66 ± 0.74)." (PMID 28537888, 2017). "In conclusion, our results provide the first evidence that ITGB1 is a direct target of miR-493-5p suggesting that ITGB1 and miR-493-5p may have potential prognostic value and may be useful as tumor biomarkers for the diagnosis of NSCLC patients." (PMID 28537888, 2017). "Taken together, our findings firstly indicate that miR-493-5p levels may play an essential role in NSCLC progression by targeting oncogene ITGB1 suggesting that ITGB1 and miR-493-5p have potential prognostic value as tumor biomarkers in NSCLC patients." (PMID 28537888, 2017). "Besides, si-ITGB1 co-transfection with HULC inhibited the tumor-promoting effect of HULC by inhibiting tumor metastasis (P<0.05) and invasion (P<0.05)." (PMID 29022892, 2017). "Many studies have indicated that ITGB1 promotes metastasis in a variety of tumor cell types." (PMID 26903137, 2016). "In addition, angiopoietin-2 can stimulate tumor cell metastasis to lymph nodes and lung, via activating tumor cell ITGB1." (PMID 27353038, 2016). "We showed that angiopoeitin-2 supported estrogen-independent tumor cell growth via ITGB1." (PMID 27353038, 2016). "ITGB1 plays an important role in the promotion of tumor cell metastasis." (PMID 26903137, 2016). "Interestingly, Imanishi and coworkers (2007, 2011) reported that angiopoeitin-2 acts directly on ER+ tumor cells via ITGB1 and promoted their initial survival and metastatic growth at lung." (PMID 27353038, 2016). "The discrepancy on biological function and clinical relevance of ITGB1 in different types of tumor may ascribe to variations of antibodies, ethnic origin, stage difference, tissue specificity, etc. which warrants further investigations to clarify." (PMID 26898710, 2016). "ITGB1, which is an important oncogene, plays a critical role in tumor invasion and metastasis." (PMID 26903137, 2016). "To find-out whether this was dependent on tumor cell ITGB1, we performed ITGB1 knockdown using shRNAs." (PMID 27353038, 2016). "Interestingly, it has been known that the activation of ITGB1 turns dormant tumor cells into awakening state." (PMID 27353038, 2016). "Additionally, ITGB1 knockdown abrogated the expression of G6PD in tumor cells." (PMID 40685383, 2025). "This indicates that ITGB1 might play a crucial role in the tumor development process." (PMID 40821990, 2025). "Moreover, the tumor weights and volumes were significantly increased in the ITGB1OE and Piezo1OE groups, while no significant changes were observed in the body weight of mice among each group, further supporting the notion that the Piezo1/ITGB1 axis contributed to tumor progression." (PMID 40667648, 2025). "However, this interaction was disrupted when the tumor cells were mixed with ITGB1-KO Jurkat cells." (PMID 40955669, 2025). "Besides, overexpression of ITGB1 led to increased tumor cell invasion." (PMID 39207055, 2024). "Additionally, ITGB1, 5, 7, and 8 decreased in metastatic sites compared with primary tumor sites." (PMID 38814534, 2024).
tumor (continued). "Excess dietary iron in tumor tissues was also associated with significant changes (generally, increases; p ≤ 0.05) in proteins involved in modulating cell protein integrity (HSPA5, HSPA9, ITGB1, PSMA4, DPP7, and PEPD), cell mobility and growth (CAPZB), and immunologic factors (FCGBP)." (PMID 38732562, 2024). "ALKBH5 promotes tumor-associated lymphangiogenesis and then LN metastasis, in which ALKBH5 stimulates downstream focal adhesion kinase (FAK)/Src proto-oncogene (Src) signalling and boosts integrin subunit beta 1 (ITGB1) expression by disrupting the YTHDF2 protein-mediated m6A degradation pathway." (PMID 36632222, 2023). "Therefore, FN1/ITGB1 may be a potential therapeutic target to target the tumor microenvironment in PTC." (PMID 37733241, 2023). "Together, these finding confirm the hypothesis that miR-29, when upregulated in the W2KO cells, downregulates ITGB1 by directly binding to its 3′-UTR, which in turn causes the cancer cells to lose their oncogenic properties in vitro and their tumor growth and metastasis promoting potentials in vivo." (PMID 36968231, 2023). "Furthermore, epithelial cells from cancerous tissues showed preferential expression of ITGB1 and CD44, which have been reported to be linked to tumor progression and could act as a receptor for SPP1." (PMID 36612160, 2022). "In addition, ITGB1 and Akt signaling are significantly related to tumor angiogenesis." (PMID 35013450, 2022). "Finally, collagen and associated signaling molecules, including ITGB1, YBX1, SPP1 and NF-κB in tumor tissues, could serve as potential biomarkers to monitor tumor progression and predict chemoresistance." (PMID 34758833, 2021). "Moreover, immunohistochemistry analysis was conducted to determine whether lnc005620 affects the expression of ITGB1 in xenograft tumor tissues." (PMID 33747911, 2021). "Moreover, downregulation of ITGB1 impaired tumor growth and peritoneal spread in in vivo assays." (PMID 32565741, 2020). "Neither CAV1 nor ITGB1 expression associated with Gleason score or pathological tumour stage (pT)." (PMID 29402961, 2018). "However, we did not observe any association between ITGB1 expression and patient age, gender, smoking history, tumor differentiation and histology (P > 0.05)." (PMID 28537888, 2017). "The results showed that NSCLC patients with high ITGB1 expression and low miR-493-5p levels had significantly decreased OS (P < 0.001), which suggested that ITGB1 and miR-493-5p might have potential prognostic value and could be useful as tumor biomarkers for the diagnosis of NSCLC patients." (PMID 28537888, 2017). "Interestingly, our previous study found that hTERT could enhance FOXO3a ubiquitination and alleviate the inhibitory effect of FOXO3a on ITGB1 expression, which finally upregulated ITGB1 expression and tumor invasion." (PMID 26689987, 2016). "Therefore, we hypothesized whether ITGB1 expression is regulated by hTERT via the control of miRNA(s), which would trigger tumor metastasis." (PMID 26903137, 2016). "Moreover, ITGB1 and Akt signaling are significantly correlated with tumor angiogenesis." (PMID 25162518, 2014). "Network visualization highlighted key gene hubs involved in these processes, including FBLN1, CAV1, FGFR4, and ITGB1, suggesting a possible role for TNBC epithelial cells in modulating the tumor immune microenvironment." (PMID 41595458, 2025). "The largest mean differences between tumor and normal tissues were observed in UEA assays ITGA2–UEA, ITGA3–UEA, and ITGB1–UEA." (PMID 40287842, 2025). "The Piezo1/ITGB1 axis activates the release of Ca2+ influx, which in turn enhances YAP signaling and its translocation into the nucleus, promoting ECM remodeling and tumor stiffness." (PMID 40667648, 2025).
tumor (continued). "Compared to the NGR-ALKBH5-siRNA-BNVs group, tumor volume and mass were significantly increased in the NGR-ALKBH5-siRNA-BNVs + ITGB1 group (p < 0.05)." (PMID 40585991, 2025). "Ligand‒receptor analysis revealed that azvudine predominantly regulated signal transduction from tumor CD4+ T cells to other immune cells through SPP1-(ITGAV + ITGB5) and SPP1-(ITGAV + ITGB1), as well as COL1A1-(ITGA9 + ITGB1), COL1A1-CD44, and COL1A1-SDC4." (PMID 39819859, 2025). "Remarkable differences between normal and tumor tissues in GalNAc‐specific WFL assays were observed in ITGA3 and ITGB1." (PMID 40287842, 2025). "Gene effect values approaching –1 suggest that suppression of ITGB1, TIMP3, or BRAF severely compromises tumor cell viability." (PMID 41294900, 2025). "Furthermore, mIHC analysis confirmed that AREG and EGFR/ERBB2, as well as NAMPT and ITGA5/ITGB1, were overexpressed in the PMC_P region, verified in clinical specimen suggesting that these LRPs play a critical role in mediating tumor initiation in the tipping point." (PMID 40976783, 2025). "The downregulation of cell adhesion proteins (ITGB1, LGALS3, LGALS3BP, SDCBP, PODXL, CDCP1) further suggests a potential impact on tumor cell attachment, migration, and invasion, contributing to the anti-metastatic effects of TSA." (PMID 40429900, 2025). "On the one hand, tumor cell C1_EGFR+ and C2_STAT1+ directly act on CD8T_GNLY+ through the MDK–(ITGA4+ITGB1) axis and the MIF–(CD74+CXCR4) axis to promote tumor proliferation." (PMID 40948762, 2025). "Cell Adhesion and Migration: CD44, ITGB1, LAMB1, FAT1, PLAUR, and TGFBI are integral to cell–matrix interactions and extracellular matrix (ECM) remodeling, processes critical for tumor invasion and metastasis." (PMID 41303451, 2025). "Three calpain substrates, ITGB1, ITGB3, and ITGB7, were subsequently selected for further study on the basis of their importance in tumor invasion and metastasis as well as the occurrence of missense mutations within the calpain cleavage site." (PMID 40362482, 2025). "The largest S/B ratios between tumor and normal tissues were observed in ITGA5–SBA, ITGA5–MAA, ITGA3–UEA, and ITGB1–SBA, each demonstrating a large overlap between normal and tumor tissues." (PMID 40287842, 2025). "We nominate CEBPD and TNFRSF1A/ITGB1 as actionable nodes and identify ARRDC3 as a spatially restricted effector with context-dependent tumor-modulatory functions warranting therapeutic exploration." (PMID 41235227, 2025). "Aberrant ITGB1 signaling enhances activation of the FAK, PI3K/AKT, and MAPK pathways, promoting tumor proliferation and survival." (PMID 41294900, 2025). "The Piezo1/ITGB1 axis significantly enhances ECM stiffness and the accumulation of collagen, which is a critical factor in the tumor microenvironment that can promote cancer cell behavior, including proliferation, migration, and invasion." (PMID 40667648, 2025). "In contrast, memory B cells expressed high levels of ITGB1, IGHA and IGHG, indicative of their role in promoting anti‐tumour immune response." (PMID 41275425, 2025). "Decreased ITGB1 expression impairs cell-ECM interactions and signaling pathways essential for cell proliferation and survival, promoting tumor cell motility, invasion, and metastasis." (PMID 40817072, 2025). "The LGALS3/JUN/ITGB1/SPP1 genes were highly expressed in MES-like GBM cells, and the expression of these genes was significantly upregulated with tumour progression." (PMID 39629136, 2024). "In CRC, Ropivacaine, an anesthetic drug, decreased the expression of ITGB1 and affected the phosphorylation of AKT/FAK/ERK, a downstream pathway of ITGB1, serving as a tumor suppressor and thereby decreasing the development and progression of CRC." (PMID 38279122, 2024). "Among stromal fibroblast cells, ITGAV, ITGA1, ITGB1, and ITGB5 were significantly upregulated following IO and, notably, isolated tumor cells found in the stroma showed upregulation of B2M, VIM, ITGA5, ITGB2, and ITGA3." (PMID 39639369, 2024).
tumor (continued). "The results showed that ITGA1, ITGB1, ITGB8 and SDC1 were highly expressed in tumor cells when compared with control group." (PMID 38526745, 2024). "SPP1 bound with integrins such as ITGB1 and ITGB5, implying the role of SPP1 in integrin signaling between fibroblasts, macrophages, and tumor cells that lead to EMT and cell-adhesion to the ECM." (PMID 39075108, 2024). "Significant correlations between ITGB1 and LGALS3 mRNA levels, and between ITGB1 and IL-10 mRNA levels, are observed in the LIHC normal and tumor tissues, and in normal liver tissues." (PMID 38793619, 2024). "To further confirm the interactive SPP1/ITGB1 signaling between TAMs and tumor cells, we conducted QIF analysis on another independent cohort involving 105 tumor tissue samples." (PMID 39207055, 2024). "Integrin beta-1 (ITGB1, CD29) and CD44, with their widespread expression in various cell types, are both key mediators of tumor invasion, metastasis, and resistance in GBM and other cancers." (PMID 39594703, 2024). "The expression of BMI1, ITGB1, HISTH1B, PXN-AS1, and LOC100128361 in OCSCC tissues and adjacent tissues of 60 patients was detected by RT-qPCR, in which the expression of BMI1, ITGB1, and PXN-AS1 was significantly elevated in tumor tissues." (PMID 38254031, 2024). "ITGB1 is increased on SCLC cells upon extensive stage of disease in mice and drives tumor cell migration." (PMID 38775153, 2024). "We further identify NRP1 and ITGB1 as pivotal functional receptors of Sema3C, activating downstream AKT/Gli1/c-Myc signaling pathways to bolster HCC self-renewal and tumor initiation." (PMID 38956074, 2024). "Previous studies have demonstrated that upregulation of ITGB1 and CD44 can promote tumor progression and invasion." (PMID 38233802, 2024). "Turning attention to the tumor, in HCC, ITGB1/PXN/YWHAZ/ AKT axis promotes HCC advancement by speeding up the cell cycle process." (PMID 38279122, 2024). "Many signals favoring tumor cells were significantly activated in C2, such as integrin-related signals (COL9A3 − (ITGA2+ITGB1), JAM3 − (ITGAM+ITGB2), COL6A1 − (ITGA1+ITGB1)), immune suppression signals (CD99 − PILRA), etc.." (PMID 39391717, 2024). "Specifically, SPP1 released from tumor cells interacted with CD44, ITGAV, ITGA5, ITGB1, and ITGB5 on immune clusters." (PMID 39505867, 2024). "Integrin 1 (ITGB1) is considered an important factor for promoting EMT and tumor invasion in a variety of tumors and also plays an important role in the progression of fibrotic diseases." (PMID 39258668, 2024). "The results from the present study, in particular, show that CD44 expression was increased in the st-FL tumor along with several members of the CD11a/b family (ITGA1, ITGA5, ITGB1, ITGAV), and all integrins were involved in cellular adhesion and migration." (PMID 39456647, 2024). "The clinical relevance of our experimental findings was supported by immunohistochemical staining analyses demonstrating that the expression of HDAC7, ITGB1, LGALS3 and CD44 was highest in GBM tumours and was negatively correlated with SOX8 expression." (PMID 39629136, 2024). "Nutrient depletion within tumor tissues is considered to promote the subnuclear accumulation and endocytosis of ligand-engaged ITGA5/ITGB1 via inhibition of mTORC1." (PMID 38892190, 2024). "In turn, CD8 Tex cells in the LN-out highly expressed TGF-β1, IFN-γ, and ITGB1, which target FN1, EGFR, CTNNB1, COL1A1, and CFLAR in tumor cells, activating downstream pathways including ERK1 and ERK2 cascade." (PMID 38519500, 2024). "RT-PCR analysis of xenograft tumor lysates revealed that the expression levels of E-cad, Slug, ITGB8, ITGB1, PCNA, and BAX showed a similar pattern to those observed in vitro, and Western blot results also confirmed these findings." (PMID 39459033, 2024). "In contrast, the cell migration and cell matrix (EMT, CAF, Pan F-TBRs) and tumor inflammation (Macrophages Bind, Hypoxia, MDSC) had significantly more enrichment in the ITGB1-high group (Wilcoxon rank-sum test)." (PMID 37007126, 2023).
tumor (continued). "Using Reactome for pathway enrichment analyses, we observed Trp2Vax and immunotherapy treatment upregulated the IL-12 responsive genes, including ITGB1, SOCS3, IFNG and STAT4 in the tumor-infiltrating CD4+ T cells (with a False Discovery Rate, FDR= 0.0016)." (PMID 36911698, 2023). "In particular, the interaction between Midkine (MDK, secreted by tumor cells) and a number of MDK-receptors (ITGA4, ITGA6, ITGB1, NCL, LRP1) on CD8+ T cells appears to be a recurrent immunosuppressive pathway seen across all three patients." (PMID 36973261, 2023). "Interestingly, although re‐introducing ITGB4 alone could not support initial DCCs seeding, restoration of ITGB4 in cells expressing ITGB1 increased visible metastatic nodules with a significantly higher tumor burden, as compared to cells expressing ITGB1 alone." (PMID 37828611, 2023). "Remarkably, analyses of MDK receptor-expressing CD8 cells (ITGA4, ITGB1, NCL) showed the opposite trend, with an increase in dysfunctional and reduction in the proliferative (tumor-targeting) populations." (PMID 36973261, 2023). "We also observed that inhibition of ITGB1 with recombinant antibodies prevented lymphangiogenesis and tumor metastasis in EOC, indicating the potential efficacy of anti-ITGB1 therapeutics in EOC." (PMID 36632222, 2023). "Gray-scale analysis by ImageJ software also showed that the expression level of normalized fucosylated ITGB1 and CD276 in tumor tissues was significantly higher than those in normal tissues." (PMID 35752862, 2022). "The SPP1 receptor ITGB1 was upregulated in tumor-derived NK cells, while another SPP1 receptor ITGA4 was upregulated in tumor-derived CTL-1 cells." (PMID 36180422, 2022). "Importantly, the combination of PODXL with ITGB1 immunohistochemically scored using resected PDAC tissues accurately predicts the postoperative prognosis of PDAC patients better than the Union for International Cancer Control (UICC) tumor node metastasis (TNM) staging system." (PMID 35275973, 2022). "Recently, there has been increased research on the relationship between ITGB1, a member of the ITG family, and tumours." (PMID 35570248, 2022). "The role of five of them (LAMB2, SERPINEE1, ITGB1, TNC, and LAMA5) in tumor growth has been well established." (PMID 35642785, 2022). "Tumor samples with more than 4 mm thickness exhibited significantly lower relative expression levels of ITGA3, ITGA6, ITGA9, ITGAV, and ITGB1 than samples belonging to the 2–4 mm Breslow thickness category (Mann–Whitney test, p < 0.05)." (PMID 36091936, 2022). "Integrin β1 (ITGB1), a member of the integrin (ITG) family, regulates tumour invasion, migration, and apoptosis." (PMID 35570248, 2022). "ITGB1 and ITGA1 were found among the key CAF receptors that mediate crosstalk between tumor cells and CAFs by interacting with COL1A1 and TNC and, thereby, modulating the TME." (PMID 36003785, 2022). "It is therefore possible that miR-134 exerts its suppression on tumor adhesion and migration in NPC via downregulation of ITGB1." (PMID 35804897, 2022). "PDIA3P negatively regulates miR-183 and influences its target ITGB1, thus inducing the activation of FAK/PI3K/AKT/β-catenin signals and affecting tumor growth and metastasis." (PMID 34947885, 2021). "Altogether, our study showed that the ITGB1/PXN/YWHAZ/protein kinase B (AKT) axis enhances HCC progression by accelerating the cell cycle process, which offers a promising approach to halt HCC tumor growth." (PMID 34977001, 2021). "The results showed that ITGB1 (4/10), ITGB3 (6/10), ITGB5 (6/10), and ITGB6 (5/10) protein levels were increased in tumour tissues compared to adjacent tissues." (PMID 34709754, 2021). "Quantitative PCR was used to examine the effects on mRNA levels of platelet-derived growth factor (PDGFB), tumor vascular marker CD105, and cell adhesion molecules ITGA5, ITGB1, and CD44." (PMID 34176441, 2021).